CUEDC2 (CUE domain containing 2)
Description:
Down-regulates ESR1 protein levels through the ubiquitination-proteasome pathway, regardless of the presence of 17 beta-estradiol. Also involved in 17 beta-estradiol-induced ESR1 degradation. Controls PGR protein levels through a similar mechanism.
Synonyms: C10orf66; MGC2491; bA18I14.5
Tractability: PROTAC: ubiquitination databases record sites on it; its protein half-life has been measured.
Gene: Protein-coding gene on chromosome 10 (102,423,242 to 102,432,718, reverse strand). Ensembl gene ENSG00000107874.
Subcellular location: Cytoplasm; Nucleus
Subcellular location (Human Protein Atlas): Cytosol; Nucleoplasm; Nuclear membrane; Plasma membrane; Primary cilium tip
Gene Ontology:
Molecular function: protein binding; ubiquitin binding
Biological process: negative regulation of cytokine production involved in inflammatory response; negative regulation of macrophage cytokine production
Cellular component: cytosol; nuclear membrane; nucleoplasm; cytoplasm; nucleus
Genetic constraint (gnomAD): Loss-of-function variants: 10 observed, 37.09 expected, observed/expected ratio (o/e) 0.27, 90% interval 0.17 to 0.46. The upper end of that interval is the gene's LOEUF score, 0.46, which puts it in group 2 of 6, group 1 being the genes least tolerant of losing a copy. Missense variants: 269 observed, 387.35 expected, observed/expected ratio (o/e) 0.69, 90% interval 0.63 to 0.77. Synonymous variants: 133 observed, 150.72 expected, observed/expected ratio (o/e) 0.88, 90% interval 0.77 to 1.02.
Homologues: Orthologues: dog CUEDC2 (95% identical), pig CUEDC2 (94% identical), chimpanzee CUEDC2 (92% identical), guinea pig CUEDC2 (89% identical), rabbit CUEDC2 (87% identical), mouse Cuedc2 (87% identical), macaque CUEDC2 (84% identical), rat Cuedc2 (75% identical), tropical clawed frog cuedc2 (49% identical), macaque CUEDC2 (44% identical), zebrafish cuedc2 (41% identical), Drosophila melanogaster CG9636 (28% identical).
Diseases named in the same sentence as CUEDC2 in open-access papers:
CUEDC2 is named in the same sentence as 25 diseases in open-access papers, as found by Europe PMC text mining. Sharing a sentence is not in itself a finding about the gene and the disease. The quoted sentences say what the papers report.
glioma (14 papers, 2019 to 2024). A benign or malignant brain and spinal cord tumor that arises from glial cells (astrocytes, oligodendrocytes, ependymal cells). "LncRNA brain cytoplasmic RNA 1 (BCYRN1) can suppress glioma tumorigenesis by binding with miR-619-5p to adjust CUE domain containing 2 (CUEDC2) expression and the PTEN/ AKT/p21 pathway." (PMID 35156508, 2022). "Our findings demonstrated that the role of the regulatory network between BCYRN1/miR-619-5p/CUEDC2 in glioma was achieved by affecting PTEN/AKT signaling pathway activity." (PMID 32978519, 2020). "Taken together, these data provided evidences that inhibition glioma progression of BCYRN1 was primarily dependent on the miR-619-5p/ CUEDC2 axis." (PMID 32978519, 2020). "We found that the CUEDC2 level was positively correlated with the BCYRN1 level in the glioma tissues." (PMID 32978519, 2020). "Our study revealed a mechanism for BCYRN1 that competitively bind miR-619-5p, in turn, suppressed glioma proliferation, migration through inactivating the CUEDC2/PTEN/AKT/p21 pathway." (PMID 32978519, 2020). "In contrast, CUEDC2 inhibits glioma neurosphere formation and the tumor cell metastasis and proliferation in glioma." (PMID 33099540, 2020). "In conclusion, our results indicated that PTEN/AKT signaling participated in BCYRN1-mediated inhibition of glioma progression via miR-619-5p/CUEDC2 axis." (PMID 32978519, 2020). "In this study, we showed that CUEDC2 was downregulated in glioma and the lower expression was more likely to be poor overall survivals, which supported that reduced level of BCYRN1 was correlated with poor prognosis." (PMID 32978519, 2020). "BCYRN1 functioned as a ceRNA to inhibit glioma progression by sponging miR-619-5p to regulate CUEDC2 expression and PTEN/AKT/p21 pathway." (PMID 32978519, 2020). "For example, CUEDC2 suppresses glioma tumorigenicity by inhibiting the activation of STAT3 and NF‐κB signalling pathway, and gp78 acts as a regulator of normal liver homeostasis and a tumour suppressor in human liver." (PMID 30771255, 2019). "In this study, it was confirmed that miR-619-5p was the direct target gene of BCYRN1, further elucidating that miR-619-5p specifically targeted the CUE domain of protein 2 (CUEDC2), while BCYRN1/miR-619-5p inhibited glioma by inactivating the PTEN/AKT/p21 pathway in a CUEDC2-dependent manner." (PMID 36124026, 2022). "In addition, our study revealed a mechanism that BCYRN1 competitively bind miR-619-5p to regulate glioma progression through inactivating the CUEDC2/PTEN/AKT/p21 pathway." (PMID 32978519, 2020). "Importantly, the miR-619-5p level was inversely correlated with the CUEDC2 level in the glioma tissues." (PMID 32978519, 2020). "CUEDC2 showed an obvious downregulation in 30 glioma samples compared to control samples." (PMID 32978519, 2020). "Upregulation of CUEDC2 could partially rescue the promotive effects of miR-619-5p on cell growth and migration, while inhibition of CUEDC2 could partially rescue the reductive effects of miR-619-5p on cell growth and migration in glioma." (PMID 32978519, 2020). "To explore the mechanism of BCYRN1/miR-619-5p in glioma progression, we performed comprehensive bioinformatic analysis using four datasets and found that 44 mRNAs might be the potential targets of miR-619-5p including CUEDC2, which was reported to be a tumor suppressor in glioma." (PMID 32978519, 2020). "Brain Cytoplasmic RNA 1 (BCYRN1) binding with miR-619-5p can regulate CUE Domain Containing 2 (CUEDC2) expression and the PTEN/AKT/p21 pathway to inhibit glioma tumorigenesis." (PMID 37239411, 2023). "lncRNA BCYRN1 plays a ceRNA role by regulating CUEDC2 expression and PTEN/AKT/p21 pathway through sponge miR-619-5p, thereby inhibiting glioma development." (PMID 37252659, 2023). "In one prior report, this lncRNA was shown to sequester miR-619-5p and to thereby upregulate CUEDC2 expression and PTEN/AKT/p21 pathway activation, thus modulating glioma cell malignancy." (PMID 35730016, 2022).
glioma (continued). "Mechanistically, miR-619-5p specifically targeted the CUE domain containing protein 2 (CUEDC2), and BCYRN1/miR-619-5p suppressed glioma tumorigenesis by inactivating PTEN/AKT/p21 pathway in a CUEDC2-dependent manner." (PMID 32978519, 2020). "High expression of BCYRN1 acts as a ceRNA, sponging miR-619-5p to regulate the expression of CUE domain-containing protein 2 (CUEDC2) and the PTEN/AKT/p21 pathway, ultimately inhibiting cell proliferation and migration of glioma cell lines, which offers new insights for glioma treatment." (PMID 38967893, 2024). "Moreover, another research discovered that lncRNA brain cytoplasmic RNA 1(BCYRN1) served as a miR-619-5p sponge to regulate the cue domain containing 2(CUEDC2) expression in the PTEN/AKT/p21 pathway; this combination reduced glioma development." (PMID 35619711, 2022). "A recent study found that BC200 could regulate CUEDC2 expression and the PTEN/AKT/p21 pathway by functioning as a ceRNA for sponging miR-619-5p to inhibit glioma progression." (PMID 35136029, 2022).
breast cancer (10 papers, 2015 to 2025). A primary or metastatic malignant neoplasm involving the breast. "CUEDC2 is associated with the progesterone receptor (PR) and is involved in the ubiquitination and degradation of PR in breast cancer." (PMID 33494071, 2021). "For example, the ubiquitin-binding protein CUEDC2 promotes ERα degradation via the proteasome pathway; consequently, malignant mammary tumors with high CUEDC2 expression under tamoxifen-resistant conditions exhibit low ERα levels." (PMID 40641933, 2025). "The Lys-388 is a key site not only for PGR-B SUMOlation, but also a key site for CUEDC2-mediated ubiquitination in proteasome in breast cancer." (PMID 35244538, 2022). "CUEDC2 was first discovered to interact with PR and promote its degradation in a ubiquitin-dependent manner in breast cancer." (PMID 36231027, 2022). "Previous studies have shown that CUEDC2 is a regulator for progesterone and estrogen receptors in breast cancer." (PMID 33494071, 2021). "CUEDC2 was reported to interact with ERα and PR and promote the ubiquitination and degradation of the receptors in breast cancer." (PMID 33099540, 2020). "CUEDC2 promotes breast cancer progression and endocrine resistance through the degradation of estrogen receptor-α (ERα) and the progesterone receptor (PR)." (PMID 33099540, 2020). "We have also reported that CUEDC2 promotes the ubiquitination and degradation of ER‐α and PR in breast cancer cells." (PMID 27286733, 2016). "As the decrease in GPX1 was not at the transcriptional level and previously reported that CUEDC2 promotes the ubiquitination and degradation of the progesterone receptor (PR) and estrogen receptor‐α (ER‐α) in breast cancer cells." (PMID 27286733, 2016). "By studying specimens from a large cohort of subjects with breast cancers, the authors found a strong inverse correlation between CUEDC2 and ERα expression." (PMID 27884978, 2016). "Further, ectopic CUEDC2 expression impaired the responsiveness of breast cancer cells to tamoxifen, implying that CUEDC2 can contribute to resistance in breast cancer." (PMID 27884978, 2016). "Hence, CUEDC2 induces ERα degradation via the UPS, and some malignant mammary tumors with resistance to tamoxifen show high levels of CUEDC2 protein with low levels of ERα." (PMID 35498431, 2022). "Our findings are valuable for the further recognition of the roles of CUEDC2 in breast cancer." (PMID 36231027, 2022). "A high expression level of CUEDC2 indicates a significant prognostic value for breast cancer patients; thus, therapeutic drug-targeted CUEDC2 should be considered as a promising approach to eradicate Wnt signaling driving cell populations and, in consequence, TNBC." (PMID 36231027, 2022). "Finally, by analyzing NF-κB network activity, it was pointed out a negative association between the expression of CUEDC2, which is associated with endocrine resistance in breast cancer, and NF-κB signaling." (PMID 27563822, 2016). "In breast cancer cells, E3 ligase BRCA1 and CUEDC2 have been shown to regulate PGR protein stability." (PMID 35244538, 2022).
lung adenocarcinoma (2 papers, 2015 to 2020). A carcinoma that arises from the lung and is characterized by the presence of malignant glandular epithelial cells. "Taken together, our results suggested that low expression of CUEDC2 is associated with tumor growth and that CUEDC2 is an independent prognostic factor for lung adenocarcinoma patients." (PMID 26023733, 2015). "Our results demonstrated that up-regulation of CUEDC2 decreases proliferation of lung adenocarcinoma cells, by inhibiting the PI3K-Akt transduction pathway and concomitant p21 up-regulation and cyclin D1 down-regulation." (PMID 26023733, 2015). "CUEDC2 expression was inversely correlated with clinical stage and tumor size in lung adenocarcinoma patients." (PMID 26023733, 2015). "Multivariate analysis suggested that CUEDC2 expression is an independent prognostic indicator for survival of lung adenocarcinoma patients." (PMID 26023733, 2015). "Low levels of CUEDC2 were correlated with a shorter survival time in patients with lung adenocarcinoma (p = 0.004)." (PMID 26023733, 2015). "Our results suggest that decreased expression of CUEDC2 contributes to tumor growth in lung adenocarcinoma, leading to a poor clinical outcome." (PMID 26023733, 2015). "To explore the possible roles of CUEDC2 in inhibiting lung adenocarcinoma cell proliferation, we measured the cell cycle distribution of CUEDC2-over-expressing cells using flow cytometry." (PMID 26023733, 2015). "We analyzed CUEDC2 expression in 112 paraffin-embedded, archived lung adenocarcinoma tissues using immunohistochemical staining with an antibody against human CUEDC2." (PMID 26023733, 2015). "Collectively, our results indicate that overexpression of CUEDC2 inhibits lung adenocarcinoma both in vitro and in vivo." (PMID 26023733, 2015). "Multivariate analysis suggested that CUEDC2 expression is an independent prognostic indicator for patients with lung adenocarcinoma." (PMID 26023733, 2015). "Here we showed that both mRNA and protein levels of CUEDC2 were significantly down-regulated in human lung adenocarcinoma cell lines and surgically-excised lung adenocarcinoma tumors." (PMID 26023733, 2015). "We found that CUEDC2 was low in lung adenocarcinoma cell lines and lung adenocarcinoma tissues at both mRNA and protein levels." (PMID 26023733, 2015). "Conversely, down-regulation of endogenous CUEDC2 significantly increased growth of lung adenocarcinoma cells by activating the PI3K-Akt singling pathway, down-regulating p21, and up-regulating cyclin D1." (PMID 26023733, 2015). "To evaluate the biological role of CUEDC2 in the proliferation of human lung adenocarcinoma cells, we generated lung cancer cells that stably expressed CUEDC2." (PMID 26023733, 2015). "Comparative analysis of CUEDC2 expression was conducted on 6 pairs of matched lung adenocarcinoma tissue and adjacent normal lung tissues." (PMID 26023733, 2015). "Ectopic expression CUEDC2 or shRNA-mediated knockdown of CUEDC2 decreased or increased, respectively, cell proliferation, indicating that CUEDC2 inhibits proliferation of lung adenocarcinoma cells." (PMID 26023733, 2015). "In summary, our data show that CUEDC2 functions as a putative tumor suppressor in lung adenocarcinoma, and that the anti-proliferative effects of CUEDC2 are mediated through its effects on the PI3K/Akt signaling pathway." (PMID 26023733, 2015). "Our results indicated that patients with low expression of CUEDC2 frequently developed larger lung adenocarcinoma tumors, consistent with an anti-proliferative role for CUEDC2 in lung cancer." (PMID 26023733, 2015). "We found significant correlation between the tumor T stage and CUEDC2 levels in lung adenocarcinoma tissues from patients." (PMID 26023733, 2015). "Notably, CUEDC2 overexpression predicted a favorable clinical outcome and a longer survival time for patients with lung adenocarcinoma." (PMID 33099540, 2020). "Next, we investigated the clinical relevance of CUEDC2 in the proliferation of lung adenocarcinoma." (PMID 26023733, 2015).
lung adenocarcinoma (continued). "In addition, silencing of CUEDC2 expression using an shRNA-mediated method increased the growth of lung adenocarcinoma cells, as assessed using the MTT and clone formation assays." (PMID 26023733, 2015). "Thus, CUEDC2 expression, at both the protein and mRNA levels, was reduced in lung adenocarcinoma cell lines and patient-derived tissues." (PMID 26023733, 2015). "Furthermore, the expression of CUEDC2 was strongly correlated with the tumor T classification (P = 0.001) and clinical stage (P = 0.002) of patients with lung adenocarcinoma." (PMID 26023733, 2015). "We concluded that CUEDC2 plays a tumor-suppressive role in lung adenocarcinoma." (PMID 26023733, 2015). "Highly-expressed CUEDC2 was mainly localized in the cytoplasm of lung adenocarcinoma cells." (PMID 26023733, 2015). "Our results demonstrate that over-expression of CUEDC2 inhibits Akt in lung adenocarcinoma cells." (PMID 26023733, 2015). "In contrast to previous reports that CUEDC2 was highly expressed in many types of cancers, our study suggested that CUEDC2 was markedly down-regulated in lung adenocarcinoma cells and surgical specimens of lung adenocarcinoma." (PMID 26023733, 2015). "Furthermore, in our study, we provided evidence that in lung adenocarcinoma, CUEDC2 expression is down-regulated, and that CUEDC2 inhibits growth of lung adenocarcinoma cells both in vitro and in vivo." (PMID 26023733, 2015). "Thus, low CUEDC2 expression is a risk factor that predicts poor survival, suggesting that decreased expression of CUEDC2 likely contributes to lung adenocarcinoma cell proliferation and might represent a prognostic biomarker for this disease." (PMID 26023733, 2015). "Thus, CUEDC2 suppressed proliferation of lung adenocarcinoma cells." (PMID 26023733, 2015). "The expression of CUEDC2 protein in three lung adenocarcinoma samples was much lower than in the paired adjacent noncancerous tissue." (PMID 26023733, 2015). "The impact of CUEDC2 expression in lung adenocarcinoma has not been elucidated." (PMID 26023733, 2015).
amyotrophic lateral sclerosis (1 paper, 2019). Amyotrophic lateral sclerosis (ALS) is a neurodegenerative disease characterized by progressive muscular paralysis reflecting degeneration of motor neurons in the primary motor cortex, corticospinal tracts, brainstem and spinal cord. "Several genes, such as CUEDC2, in CSF exosomes were suggested to be candidate disease biomarkers for amyotrophic lateral sclerosis." (PMID 30630471, 2019). "In comparison with exosomal mRNAs in CSF from four patients with amyotrophic lateral sclerosis, 543 genes were significantly changed, as represented by CUEDC2." (PMID 30630471, 2019).
cardiac hypertrophy (1 paper, 2016). "HW/BW ratio, an index of cardiac hypertrophy (CH), was not different between young WT and Cuedc2−/− mice and was significantly elevated in old WT mice, but not in old Cuedc2−/− mice." (PMID 27286733, 2016).
cardiomyopathy (1 paper, 2016). A disease of the heart muscle or myocardium proper. "Together, these results indicate that the ablation of CUEDC2 mitigates ageing‐induced cardiomyopathy by suppressing the abnormal accumulation of ROS in the myocardium." (PMID 27286733, 2016). "Ageing cardiomyopathy is also characterized by increased apoptosis, which was observed in the present study in the old WT mice, but much less in the Cuedc2−/− mice." (PMID 27286733, 2016). "Therefore, CUEDC2 represents an ideal therapeutic target to treat MI and ageing‐induced cardiomyopathy." (PMID 27286733, 2016).
colon tumors (1 paper, 2016). "Elevation of miR-324-5p levels results in decreased expression of CUEDC2 in macrophages infiltrated in mouse colon tumors and isolated from fresh colon tumor samples, which produces excess tumor-promoting cytokines and promotes pathogenic progress of CRC." (PMID 26964533, 2016).
fibrosis (1 paper, 2016). the formation of excess fibrous connective tissue in an organ or tissue in a reparative or reactive process. "Myocardial fibrosis, an important index of detrimental remodeling, was also increased in WT old mice vs WT young mice, and this was significantly attenuated in the old Cuedc2−/− mice." (PMID 27286733, 2016).
ischemia (1 paper, 2016). A hypoperfusion of the BLOOD through an organ or tissue caused by a PATHOLOGIC CONSTRICTION or obstruction of its BLOOD VESSELS, or an absence of BLOOD CIRCULATION. "However, gene transfer of higher doses of rAAV9‐CUEDC2 resulted in higher amounts of CUEDC2 remaining after 6 h of reperfusion following 30‐minute ischemia." (PMID 27286733, 2016). "Consistent with wild‐type mice, CUEDC2 delivered into the myocardium could also be degraded after 6 h of reperfusion following 30‐min ischemia." (PMID 27286733, 2016). "Compared with that observed in the non‐ischemic distant zone (DZ) and normal controls, where cardiomyocytes do not suffer from ischemia, the protein level of CUEDC2 was significantly reduced in the ischemic border zone (BZ), where cardiomyocytes struggle to survive under ischemia." (PMID 27286733, 2016).
leukaemia (1 paper, 2018). "Because the leukaemia-granulocyte macrophage progenitor (L-GMP) population of this AML model was enriched for LSCs21, we also assessed whether the CUEDC2 deficiency affected L-GMP frequency." (PMID 29991678, 2018).